MEG3 (maternally expressed 3)
Diseases named in the same sentence as MEG3 in open-access papers (continued):
Sharing a sentence is not in itself a finding about the gene and the disease.
retinopathy (3 papers, 2023 to 2025). "Similarly, MEG3 upregulation effectively suppresses the development of retinal neovascularization in mice with oxygen-induced retinopathy through downregulation of PI3K, serine/threonine kinase, vascular endothelial growth factor (VEGF), and proinflammatory factors." (PMID 39529988, 2024).
benign tumor (2 papers, 2016 to 2017). "We found that the expression of Meg3 was reduced significantly in primary tumors as compared to normal ovarian tissue and benign tumors." (PMID 28423647, 2017).
blood cancer (2 papers, 2021). "According to OpenArray results, LINC01268, HOXB-AS3, MEG3 and TCL6 transcripts were selected since deregulated in CD34+ stem/progenitor cells; further lncRNAs have been selected for their associations with myeloid differentiation and deregulation in blood neoplasms." (PMID 34638230, 2021).
central nervous system diseases (1 paper, 2023). "The top five predicted drugs that might upregulate MEG3 include RN-1734, a TRPV4 antagonist that was shown to reduce demyelination in central nervous system diseases as well as inhibit glial activation and IL-β and TNF-α production." (PMID 36869839, 2023).
digestive system neoplasm (1 paper, 2022). A neoplasm (disease) that involves the digestive system. "Characterization of MEG3 function in respiratory and digestive system neoplasms." (PMID 36544907, 2022).
intestinal ulcer (1 paper, 2021). "Consistently, over-expression of MEG3 has been shown to relieve the severity of the intestinal ulcer, mitigate mucosal epithelial cell damage, and further alleviate inflammatory cell infiltration in UC rats, which is much in accordance with our findings." (PMID 34895044, 2021).
psychiatric disorder (1 paper, 2024). A disorder characterized by behavioral and/or psychological abnormalities, often accompanied by physical symptoms. "The action mechanism of lncRNA MEG3 is associated with neuroinflammatory responses, rendering it a potential biomarker for neuroinflammation and a prospective class of biomarkers for psychiatric disorders." (PMID 39456775, 2024).
MEG3 also shares sentences with these, for which no sentence is quoted: Wilms tumor (6 papers); diabetic cardiomyopathy (5); pheochromocytoma (4); chronic hepatitis B (3); idiopathic pulmonary fibrosis (3); neurological diseases (3); pulmonary arterial hypertension (3); ulcerative colitis (3); autism (2); breast invasive carcinoma (2); Cachexia (2); colorectal adenocarcinoma (2); glaucoma (2); hemangioma (2); immune system diseases (2); lung diseases (2); lymphoma (2); multiple sclerosis (2); Non-Alcoholic Fatty Liver Disease (2); parathyroid tumors (2); retinopathy of prematurity (2); small cell lung carcinoma (2); acute leukemia (1); acute myocardial infarction (1); acute pancreatitis (1); acute respiratory distress syndrome (1); adenocarcinoma (1); alcohol abuse (1); amyloid (1); anaplastic thyroid cancer (1).
A further 72 diseases each share a sentence with MEG3 in 1 paper.